SMAD3 (SMAD family member 3)
Diseases named in the same sentence as SMAD3 in open-access papers (continued):
Sharing a sentence is not in itself a finding about the gene and the disease.
asthma (continued). "The identification of SMAD3 as an epigenetic predictor of childhood asthma at birth suggests that the early epigenetic trajectory to asthma proceeds at the intersection between immune regulation and lung development." (PMID 36073598, 2022). "There is also abundant evidence supporting an association between WPM and asthma, including that WPM induces pulmonary fibrosis via TGF-β1/Smad3 signaling in a murine model of asthma." (PMID 35837279, 2022). "SMAD3 dependent TGF-β1 signaling has been validated to play a predominant role in airway remodeling in asthma." (PMID 36008606, 2022). "Collectively, our studies identified a functional axis of AhR–RhoA that regulates the activation of TGFβ1/Smad3 signaling, thereby leading to the development of allergic airway inflammation and asthma." (PMID 33936062, 2021). "Fangxiao Formula inhibits TGF-β/Smad3 signaling pathway to alleviate airway inflammation and remodeling in rats with asthma." (PMID 34519263, 2021). "Results showed that TGFβ1 and p-Smad3 expression substantially increased in the airways of mice with acute asthma induced by OVA compared with normal mice." (PMID 34671356, 2021). "Another large-scale GWAS for asthma has identified six asthma-susceptible loci, including IL1RL1/IL18R1, SMAD3, ORMDL3/GSDM, IL-33, IL2RB, and HLA-DQ." (PMID 34946955, 2021). "Congruently, in our analysis, we also observed the SMAD3 gene to lie within DMRs both in asthma and, interestingly, COPD macrophages." (PMID 33076907, 2020). "MiR-744 repressed bronchial epithelial cell proliferation by regulating Smad3 via targeting TGF-β1 in severe asthma." (PMID 32065213, 2020). "In the present study, we investigated the expression and the roles of miR-203a-3p and SIX1 in asthma, and elucidated the regulatory relationship among miR-203a-3p, SIX1 and Smad3 in the development of asthma." (PMID 32065213, 2020). "In a previous pathway analysis of asthma, SMAD3 has been shown to interact with the WNT signaling pathway." (PMID 30061609, 2018). "The 15q21 has already been described in GWA of asthma, with the most associated genes being RORA, SMAD3 and SCG3." (PMID 26635092, 2015). "Genome-wide association (GWA) studies on asthma have suggested that several polymorphisms in several genes, including ORMDL3-GSDMB, DENND1B, HLA-DP, SLC30A8, IL1RL1-IL18R1, IL33, SMAD3, TSLP, and NOTCH4 are associated with asthma." (PMID 23861779, 2013). "They observed associations with asthma, particularly childhood-onset asthma, at multiple loci (ORMDL3/GSDMB, IL1RL1/IL18R1, HLA-DQ, IL33, SMAD3, and IL2RB)." (PMID 23028483, 2012). "Studies have shown that reducing TGF-β1 expression and inhibiting SMAD3 phosphorylation may alleviate airway remodeling in asthma." (PMID 40264707, 2025). "Interestingly, single nucleotide polymorphisms at or near the TGFBR1, SMAD3, and SMAD6 loci are linked to asthma risk, and at least 1 such polymorphism localizes to an open chromatin region in human MCs." (PMID 39744949, 2025). "This SNP rs56375023 [SMAD3] was associated with blood eosinophil counts in both the general and asthma populations, low FEV1/FVC in the general population and IgE sensitisation in the asthma population." (PMID 37186423, 2023). "Furthermore, it decreased OVA-specific IgE and IL-4 levels in serum, relieved airway remodeling, attenuated subepithelial collagen deposition, and downregulating TGF-β1and Smad3 expression in mice with asthma." (PMID 34804018, 2021). "Additionally, some studies have shown that Sirt6 attenuates the EMT process in some diseases, such as suppressing the TGF-β1/Smad3 pathway and c-Jun in an asthma model or inactivating the TGF-β1/Smad2 pathway in bronchial epithelial cells." (PMID 34122724, 2021). "For example, whole blood QTLs related to genes known to affect asthma pathogenesis or severity (e.g. IL18R, ZFP57, BTN3A2, NDFIP1, SMAD3, CLEC16A, and TSLP) were associated with colocalization sites for asthma and neutrophil, eosinophil, monocyte and/or lymphocyte traits." (PMID 32600345, 2020).
asthma (continued). "Importantly, functional validation of GWAS candidate asthma risk genes have uncovered key roles in HRV infection susceptibility (ORMDL3 and CDHR3) and TGFβ signalling (GSDMB, TGFBR1, and SMAD3)." (PMID 32887352, 2020). "Distinct genetic loci, including mothers against decapentaplegic homolog 3 (SMAD3), DENN domain containing 1B (DENND1B), and Solute carrier family 22, member 4/5 [SLC22A4/5 (5q31/IBD5)], are known to be associated with both CD and asthma." (PMID 32181078, 2020). "In two GWAS meta‐analyses, SMAD3 SNP (rs17228058, A‐> G) was a susceptibility locus of asthma and self‐reported allergy and, asthma with co‐existing hay fever, but not asthma alone." (PMID 33133517, 2020). "Exposure to rOPN could induce the expression of Tgfβ1 and the release of TGF-β1, IL-5, IL-13, and phosphorylated Smad3 in a mouse model of virus-induced asthma exacerbation." (PMID 32009132, 2020). "Moreover, an association with both asthma and Crohn’s disease was found for gene loci DENND1B, SMAD3 and SLC22A4/5 (5q31/IBD5), while the ORMDL3 gene variants present in Crohn’s disease and ulcerative colitis were also associated with childhood-onset asthma." (PMID 37835065, 2023). "Importantly, the finding that SMAD3 methylation patterns are increased at birth in children who develop asthma at age 9 suggests that progression towards asthma may begin in utero." (PMID 32887352, 2020). "Asthma is a disease with demonstrated heritability in humans, and several genes, including the IKZF3-ZPBP2-GSDMB-ORMDL3 locus, HLA-DQ, IL1RL1, IL33, TSLP, SLC22A5, SMAD3, and RORA have been consistently associated with asthma in genome-wide association studies (GWAS)." (PMID 23984888, 2013). "Genes shared between endometriosis, uterine fibroids, ovarian and endometrial cancer, asthma and migraine (CDC42, WNT4, SMAD3, SKAP1) were enriched in cell adhesion pathways." (PMID 37159502, 2023). "Recent studies have found that BMPR-II, SMAD3, and MRTF are all expressed in ASMCs in asthma models." (PMID 36008606, 2022). "Recently, several reports in the literature have correlated certain signaling molecules, include SMAD3, BMPR-II, and MRTF, to asthma progression." (PMID 36008606, 2022). "These were in loci previously associated with asthma exacerbations (GSDMB, RAD50, HLA‐DQB1, ADAM33, VDR, and CDHR3) or moderate‐to‐severe asthma (IKZF3, TSLP, MUC5AC, C11orf30, SMAD3, and WDR36)." (PMID 35754128, 2022). "In asthma, miR-203a-3p has been shown to regulate TGF-β1-induced epithelial–mesenchymal transition (EMT) by regulating the SMAD3 signaling pathway." (PMID 36264868, 2022). "Our experiments first revealed that BMPR-II (2.02 times in asthma vs. control groups), SMAD3 (2.14 times in asthma vs. control groups), and MRTF (1.45 times in asthma vs. control groups) are highly expressed in ASMCs in our asthma model." (PMID 36008606, 2022). "A variety of smooth muscle-specific genes and proteins, including SMAD3, BMPR-II, and MRTF, are involved in airway remodeling in asthma." (PMID 36008606, 2022). "TWAS genes of known biological interest in asthma include IL1RL1 on 2q12, TLR1 on 4p14, TSLP on 5q22, SMAD3 on 15q22-q23, and IL4R on 16p12." (PMID 34103634, 2021). "This previous study identified genes on chromosomes 2 (IL1RL1/IL18R1), 6 (HLA-DQ), 9 (IL33), 15 (SMAD3), 17 (ORMDL3/GSDMB), and 22 (IL2RB) correlated with asthma." (PMID 32512817, 2020). "SMAD3 is involved in TGF-β signalling, related to airway remodelling in asthma." (PMID 42316380, 2026). "Previous studies have shown there is a direct link between SMAD3 and MRTF in asthma." (PMID 36008606, 2022). "qPCR and western blots results demonstrated that mRNA and protein expression levels of SMAD3 and its phosphorylation type pSmad3 were significantly upregulated in airway smooth muscle layer and ASMCs from asthma model rats compared to non-asthma rats." (PMID 36008606, 2022).
asthma (continued). "Furthermore, we found the SMAD3 (SMAD family member 3) gene, among others, to lie within differentially methylated regions which has been previously reported in the context of asthma." (PMID 33076907, 2020). "Our findings demonstrated that miR-203a-3p was down-regulated in asthma serums, and overexpressed miR-203a-3p inhibited TGF-β1-induced EMT in asthma by regulating Smad3 pathway through targeting SIX1, suggesting a promising therapeutic approach for bronchial epithelial cell EMT in asthma." (PMID 32065213, 2020). "The upregulation of OPN may be attributed to the aging process and viral infections in older subjects with asthma, which can accelerate airway remodeling by enhancing TGF-β1/Smad3-related pathways in the pathogenesis of LOA." (PMID 32009132, 2020). "Similarly, genes shared between endometriosis, uterine fibroids, ovarian cancer, migraine and depression (RHOA, FOXP1, ESR1, WNT4, GREB1, FSHB), and endometriosis, migraine and asthma (IGF1, SMAD3, MFHAS1), were enriched in hormone receptor signalling and inflammation pathways, respectively." (PMID 37159502, 2023).
fibrosis (68 papers, 2013 to 2026). the formation of excess fibrous connective tissue in an organ or tissue in a reparative or reactive process. "The dysregulation of TGF-β1/Smad pathway was an important pathogenic mechanism in tissue fibrosis and Smad2 and Smad3 are the two major downstream regulator that promote TGF-β1-mediated tissue fibrosis." (PMID 33896391, 2021). "SMAD3 activity has mainly been implicated in cardiac fibrosis and poor outcome after ischemic injury." (PMID 34404849, 2021). "In contrast, the ubiquitin-like protein HLA-F adjacent transcript 10 (FAT10) mediates cardiac fibrosis through Smad3 in MI." (PMID 40969268, 2025). "In conclusion, the activation of TGF-β/Smad3 signaling is responsible for loss of GPX4 and the development of ferroptosis-associated fibrosis in the fibrotic kidney of patients and mice with CKD." (PMID 41079940, 2025). "When the TGF-β and SMAD3 mRNA levels were compared, the SMAD3 mRNA levels were determined to be higher in the fibrosis control group." (PMID 39055873, 2024). "TGF-β/Smad3 signaling functions in hepatic fibrosis by activating hepatic stellate cells (HSCs) and ECM accumulation." (PMID 38434258, 2024). "The existing literature strongly supports the upregulation of p-Smad3 expression in the UUO fibrosis model, intensifying fibrosis development." (PMID 38791272, 2024). "Although additional research is required to fully understand Smad2 and Smad3 involvement in intestinal fibrosis, it is reasonably inferred that TGF-β is involved in intestinal fibrosis development, as well as in other organs." (PMID 37505742, 2023). "TGFβ1 and pSmad3/Smad3 were significantly elevated in the diabetic animal model established in this study, which also suggested that the glomerular fibrosis of DKD was closely related to the TGFβ1/Smads pathway." (PMID 35126820, 2022). "In our study, we proved that TGF-β1 and Smad3 expressed much more in fibrosis model groups than in control groups, and at the same time, apigenin groups obviously reduced the expression of TGF-β1, Smad3, and the other related proteins." (PMID 33574836, 2021). "Inhibition of the TGF-β1/SMAD3 signaling pathway ameliorates non-alcoholic steatohepatitis, tubulointerstitial fibrosis, and myocardium infraction." (PMID 34149434, 2021). "In conclusion, upregulation of clusterin in the fibrotic liver can be a protective response whatever the cause of fibrosis, and clusterin reduces hepatic fibrosis by inhibiting HSC activation and Smad3 signaling pathways." (PMID 31739636, 2019). "In the same context, MPOE-treated group 3 showed marked reductions in TGF-β1 and SMAD3 proteins expression compared to the CCl4 fibrosis group." (PMID 29849890, 2018). "In conclusion, the present study demonstrated for the first time that HSF1 acts as a novel negative regulator of cardiac fibrosis by blocking Smad3 activation." (PMID 28091697, 2017). "We showed for the first time that HSF1 acts as novel negative regulator of cardiac fibrosis by blocking Smad3 activation." (PMID 28091697, 2017). "Here, Smad3 was found to be relatively highly expressed in a mouse fibrosis model, and cell lines, and this expression was decreased by miR-489 overexpression." (PMID 27506999, 2016). "Resveratrol activates SIRT3, which then ameliorates cardiac fibrosis and improves cardiac function via the transforming growth factor-β/Smad3 pathway." (PMID 27840668, 2016). "The results show TGF‐β1‐induced mesangial matrix expansion, tubulointerstitial fibrosis, and tubular basement membrane thickening that are attenuated by Smad3 deletion, whereas TGF‐β1‐induced glomerular basement membrane thickening is not shown." (PMID 24744860, 2013). "Schematic illustration of METTL3/Smad3 axis in M2‐driven MMT in CAR‐related fibrosis." (PMID 39869489, 2025). "The TGF-β1/SMAD3 signal pathway plays a central role in the pathogenesis of tissue fibrosis." (PMID 39055873, 2024).
fibrosis (continued). "Such protective abilities may derive from the inhibition of cardiac and vascular fibrosis by suppressing TGF-β1/Smad3 signaling pathway as well as activating Akt/eNOS signaling pathway." (PMID 33969019, 2021). "It is also possible that up‐regulation of miR‐21 may inhibit cardiac Smad7 expression, resulting in Smad3‐mediated cardiac fibrosis and inflammation as seen in Smad3 WT‐db/db and Smad+/−db/db mice." (PMID 33733577, 2021). "Therefore, we have set the stage for future research focus on a causal link between the observed downregulation of miRNAs and the changes in the expression of TGF-β1, Smad2, Smad3, and Smad7 mRNA, involved in cardiac fibrosis and remodeling." (PMID 28698735, 2017). "As stress-induced Smad3 activation and nuclear translocation play critical roles in cardiac fibrosis and remodeling, our finding of HSF1-mediated Smad3 inhibition prompted us to examine whether HSF1 directly interacted with Smad3." (PMID 28091697, 2017). "Fibrosis onset was not, however, linked to traditional profibrotic cytokines, and Smad3−/− mice showed comparable pathology to WT mice." (PMID 24412616, 2014). "Therefore, Smad3 and Smad2 play a distinct role in cardiac fibrosis in the infarcted heart." (PMID 37449045, 2023). "Furthermore, Smad3 plays a critical role in cardiac fibrosis." (PMID 36778114, 2023). "CCR2+ macrophage depletion markedly suppressed myocardial fibrosis, collagen deposition, and aberrant TGF-β/SMAD2/SMAD3 signaling activation in the hearts of DIC mice." (PMID 41208882, 2025). "R-Smads include Smad2, Smad3, Smad1, Smad5, and Smad8, with Smad2 and Smad3 being the key downstream mediators of TGF-β-induced tissue fibrosis." (PMID 40655154, 2025). "Sinomenine (Alkaloid; found in Sinomenium acutum) also had anti-oxidative and anti-fibrosis effects with inhibition of Smad3 in UUO mice model and TGF-β/H2O2-induced in vitro fibrosis model." (PMID 40354602, 2025). "Notable reductions in the cardiac fibrosis area, collagen deposition, and TGF-β/SMAD2/SMAD3 activation were also observed in DMF-treated DIC model mice." (PMID 41208882, 2025). "In the current study, the SMAD2, SMAD3, and SMAD4 mRNA expression levels were determined to be increased, and the SMAD7 mRNA expression level was decreased in the fibrosis control group." (PMID 39055873, 2024). "The SMAD2, SMAD3, and SMAD4 mRNA expression levels were increased and the SMAD7 mRNA expression level was decreased in the fibrosis control group." (PMID 39055873, 2024). "Numerous studies support our findings, showing that ISO induces cardiac fibrosis and plays a role in the upregulation of TGF-β/Smad2/Smad3 expression in cardiac tissues in a rat model of ISO-induced MI." (PMID 36964489, 2023). "Previous studies have demonstrated that metformin reduced cardiac fibrosis by inhibiting TGF-β1 and Smad3 pathway." (PMID 37569355, 2023). "In conclusion, ADAM17 knockdown attenuates while ADAM17 overexpression aggravates cardiac fibrosis via regulating ACE2 shedding and myofibroblast transformation through TGF-β1/Smad3 signaling pathway in diabetic mice." (PMID 36313337, 2022). "In animalstudies, empagliflozin exhibited the ability to mitigate cardiac fibrosis in itsinitial stages following an AMI, through the inhibition of thetransforming growth factor-β1 (TGF-β1)/Smad3 fibrosis pathway, unrelated to the medication’s hemodynamiceffects." (PMID 40026522, 2025). "Treatment with piperine abolished these effects successfully and resulted in significantly elevated liver expression level of smad-7 with 3.1 folds compared to the fibrosis group and suppression of the expression levels of smad-3 and TGF-β1 by 40.9 and 49.4% compared to the fibrosis group." (PMID 34778375, 2021). "Neither Smad2 nor Smad3 expression was affected, but p-Smad2 and p-Smad3 were both significantly increased in the fibrosis model groups." (PMID 28839277, 2017).